CD276 (CD276 molecule)
Diseases named in the same sentence as CD276 in open-access papers (continued):
Sharing a sentence is not in itself a finding about the gene and the disease.
bladder cancer (25 papers, 2015 to 2025). "CD276 is markedly upregulated in bladder cancer and associated with severe pathological features, advanced disease, potential for metastasis, and diminished survival rates." (PMID 39319055, 2024). "We concluded that in UM-UCs, the main regulatory pathways controlling the CD276 expression are associated with its promotor and transcription, while in other bladder cancer cells, the regulatory effects of micro-RNAs on CD276 protein expression were observed." (PMID 35563359, 2022). "We examined the relationship between tumor CD276 levels and clinical outcomes and prognosis of bladder cancer." (PMID 39319055, 2024). "Data from another GEO dataset, GSE7476, further confirmed that CD276 expression is higher in bladder cancer tissues compared to adjacent normal tissues (p<0.05)." (PMID 39319055, 2024). "We also extracted CD276 expression data for 9 bladder cancer tissues and 3 adjacent normal tissues from the GEO dataset GSE7476." (PMID 39319055, 2024). "We performed validation in both bladder cancer and renal cancer cell lines and similarly found that CD276 expression in tumor cells was significantly higher than in normal urothelial cells and renal tubular epithelial cells." (PMID 39766794, 2024). "Our analysis further confirmed that CD276 expression was significantly higher in bladder cancer tissues compared to adjacent normal tissues (7.769 ± 0.276 vs. 7.303 ± 0.161, p=0.022)." (PMID 39319055, 2024). "Beyond molecular biomarkers like CD276, recent studies have underscored the significance of the urinary microbiome in bladder cancer." (PMID 39319055, 2024). "To test that, we first used CRISPR/Cas9 to delete CD276 in MB49 cells (CD276-SG), a mouse bladder carcinoma cell line, and validated CD276 KO by Western blotting." (PMID 38561369, 2024). "The elevated expression of CD276 was reported on a variety of cancer cells, including bladder cancer cells." (PMID 35563359, 2022). "Using consecutive paraffin sections an exact co-expression of CD276 and Ki67 was recorded in metastases of bladder cancer." (PMID 35563359, 2022). "In this study, we explored the expression levels of CD276 and other bladder cancer stem cell markers including ALDH1, CD24, and CD44 as a function of cellular proliferation on UM-UC bladder cancer cells and NUCs." (PMID 35563359, 2022). "Our recent studies provided evidence that elevated CD276 expression is recorded in all stages of bladder cancer." (PMID 35563359, 2022). "The pathways regulating CD276 cell surface presentation on UM-UCs and on other bladder cancer cells must await additional experiments." (PMID 35563359, 2022). "We conclude that the individual UM-UC lines seem to represent a cohort of bladder cancer cell clones with different; quite variable CD276 expression levels." (PMID 35563359, 2022). "We therefore investigated CD276 expression in bladder cancer (BC) cells and in tissue samples of BC stages from pT2 to pT4." (PMID 33845814, 2021). "Elevated expression of CD276 in bladder cancer samples was reported previously and success of experimental anti-CD276 antibody therapies raised hope for a new immune checkpoint therapy." (PMID 33845814, 2021). "Median expression of CD276 is significantly elevated in bladder carcinoma tissue but presents with a high inter-individual variability among patient samples." (PMID 33845814, 2021). "A single-gene GSEA analysis on TCGA-BLCA data was performed to explore potential pathways through which CD276 might influence bladder cancer." (PMID 39319055, 2024). "In addition to CD276, which we have introduced, there are other urinary biomarkers for bladder cancer that have been used in clinical settings." (PMID 39319055, 2024). "In bladder cancer tissue elevated expression of immune checkpoint antigens such as programmed cell death protein-1 (PD-1; =CD279), its ligand, PD-L1 (=CD274), anti-cytotoxic T-lymphocyte associated antigen-4 (CTLA-4, =CD152), and B7-H3 (=CD276) was observed." (PMID 35563359, 2022).
bladder cancer (continued). "In addition, paraffin sections from bladder cancer tissue and metastases in lymph nodes were investigated for expression of CD276, CD24, and CD44." (PMID 35563359, 2022). "A detailed study on mechanisms contributing to enhanced transportation of CD276 to the cell surfaces may provide new aspects of upregulation of this immune checkpoint antigen in bladder cancer." (PMID 35563359, 2022). "The elevated expression of CD276 was considered a bladder cancer stem cell marker." (PMID 35563359, 2022). "However, the immune checkpoint molecule CD276 seems a rather dependable tool complementing cancer research when investigating both samples from bladder cancer tissue versus metastases." (PMID 35563359, 2022). "In bladder cancer cells, CD276-mediated activation of PI3-Kinase-dependent pathways was observed." (PMID 35563359, 2022). "Additionally, CD276 may promote the development and progression of bladder cancer through ECM-related pathways." (PMID 39319055, 2024). "This complex regulation may account for the observed differences between CD276 gene expression and B7‐H3 protein levels in relation to pCR in bladder cancer patients, emphasizing the importance of directly assessing protein expression when investigating potential biomarkers." (PMID 39539559, 2024). "We hypothesize that pathways regulating CD276—a bladder cancer cell and/or stem cell marker—are distinct and regulated independently from the other cancer stem cell markers investigated—i.e., CD24, CD44, and the ALDH1 paralog A1—and independent from the regulation of cell proliferation." (PMID 35563359, 2022). "When analyzing bladder cancer tissue samples by immunohistochemistry or other antibody-dependent methods, low protein expression may therefore underscore the immunological potential of CD276." (PMID 35563359, 2022). "Emerging targets, such as B7-H3 (CD276) and ERBB3 (HER3), have received extensive attention due to their specific expression and cancer-promoting mechanisms in bladder cancer." (PMID 40433388, 2025). "In all paraffin sections investigated, some cells expressed CD276, but only weak signals were observed for CD47 expression in one of three bladder-cancer samples." (PMID 35628262, 2022). "We therefore investigated the expression of CD276 as well as CD24 and CD44 in lymph node metastases of bladder cancer patients in comparison to bladder cancer samples." (PMID 35563359, 2022). "In contrast, a rather strong expression of CD24 was found at least in some areas of bladder cancer samples, but only a few cells expressed CD44 at barely noticeable levels, while CD276 positive cells were found in all samples." (PMID 35563359, 2022). "Another study has also shown that bladder cancer with high APOBEC3B expression has a better prognosis compared to those with low expression, and higher infiltration of various immune cells and expression of immune checkpoints, including CD276." (PMID 38827321, 2024). "We conclude that CD24pos bladder cancer stem cells are not enriched in metastases of lymph nodes, but CD276 is found on both sides." (PMID 35563359, 2022). "CD276 expression was found in urothelial cells but not in the connective tissue layers of histologically normal appearing bladder in bladder cancer patients." (PMID 33845814, 2021). "Our in vitro data using the well-established bladder cancer cell lines HT1197, TCCsup, RT4, and 5637 in comparison to four urothelial cell populations generated from explants from healthy ureters corroborated a significant overexpression of CD276 in BC cell lines." (PMID 33845814, 2021).
cervical carcinoma (25 papers, 2011 to 2026). A carcinoma arising from either the exocervical squamous epithelium or the endocervical glandular epithelium. "We observed a significant increase in the expression of multiple immune checkpoints across different risk subtypes of cervical cancer, including CD276 and NRP1." (PMID 40517358, 2025). "First, to confirm previous reports of a tumorigenic role for B7-H3 protein expression, we used CRISPR/Cas9 to knockout CD276 (B7-H3) expression in HeLa cervical cancer cells." (PMID 38182652, 2024). "Intriguingly, we found that the IPO7 expression was negatively correlated with CD8 T cell infiltration via regulating the expression of CD276 in cervical cancer." (PMID 34650978, 2021). "TISIDB was employed to examine immune infiltration in cervical cancer, revealing that IDO1 levels exhibit a significantly positive association with ICOS, C10orf54, CD27, CD28, CD70, and other immunostimulatory factors, which negatively regulate the expression of CD276." (PMID 39312339, 2024).
clear cell renal cell carcinoma (25 papers, 2009 to 2026). "This study aimed to investigate the role of cluster of differentiation 276 (CD276) in evaluating the prognosis of clear cell renal carcinoma (ccRCC) and to build a nomogram for predicting ccRCC progression post‐surgery." (PMID 39210603, 2024). "Such a conversion of CD276 expression has been observed in clear cell renal cell carcinoma." (PMID 33845814, 2021).
leukemia (25 papers, 2016 to 2026). A malignant (clonal) hematologic disorder, involving hematopoietic stem cells and characterized by the presence of primitive or atypical myeloid or lymphoid cells in the bone marrow and the blood. "CD276 (B7-H3) is highly expressed in leukemia cells of AML patients, FC optimized CD276 mAb specifically binds to CD276 on primary AML cells, promoting activation and enhancing anti-AML effects of NK cells." (PMID 40726987, 2025). "To address the question of persistence, we further characterized the BiCisCAR T cells in vivo by measuring the proportion of CAR T cells in mouse spleens 21 days after CAR T cell infusion in our model of NALM6 leukemia cells expressing either GPC2 or CD276." (PMID 35852863, 2022). "A particularly striking example of BiCisCAR T cells’ ability to prevent tumor escape was demonstrated with a heterogeneous metastatic model, where NALM6 leukemia cells expressing either GPC2 or CD276 were mixed in a 1:1 ratio and injected into mice." (PMID 35968786, 2022). "Importantly, in vivo imaging showed that both 2.5 × 106 and 5 × 106 doses of BiCisCAR T cells completely eradicated leukemia expressing GPC2 or CD276 and prevented the recurrence of leukemia." (PMID 35852863, 2022). "We focused on highly expressed antigens found in primary leukemia and lymphomas, such as CD19, CD20, CD22, ROR-1, CD276, CD79B, and CD10." (PMID 36289682, 2022). "Both GPC2 and CD276 CAR T cells failed to control tumor growth, due to the dominance of CD276+ and GPC2+ cells respectively, whereas the BiCisCAR T cells were able to completely eradicate leukemia and prevent recurrence." (PMID 35968786, 2022). "Since NSG mouse-based assessment of GVL effect on human leukemia cells or cell lines by unmanipulated human hematopoietic cells has not been established, we could not demonstrate direct evidence whether CD45RA/CD276 depletion negatively impacts GVL or not." (PMID 33976380, 2021).
rhabdomyosarcoma (19 papers, 2008 to 2026). A rare aggressive malignant mesenchymal neoplasm arising from skeletal muscle. "Here authors identify CD276 as target in childhood rhabdomyosarcoma, which, when combined into a bicistronic construct with a known target, FGF4R, allows enhanced tumour killing." (PMID 39043633, 2024). "In rhabdomyosarcoma PDX models, CD276 targeting CAR T-cells (CD276.8HTM.BBz) significantly decreased tumour volume." (PMID 40983796, 2025). "Furthermore, CD276-pyrrolobenzodiazepine increased event-free survival with exceptional responses in PDX models of embryonal and alveolar rhabdomyosarcoma and Ewing sarcoma." (PMID 40983796, 2025).
triple-negative breast carcinoma (19 papers, 2016 to 2025). An invasive breast carcinoma which is negative for expression of estrogen receptor (ER), progesterone receptor (PR), and human epidermal growth factor receptor 2 (HER2). "Abnormal fucosylation of CD276 has been reported in triple negative breast cancer (TNBC) and oral squamous cell carcinoma, and can inhibit the immune response in TNBC." (PMID 35752862, 2022). "Based on these principles, two preclinical studies were recently described with 212Pb-225.28 for the targeting of chondroitin sulfate proteoglycan 4 (CSPG4) overexpressed in triple-negative breast cancer and 212Pb-376.96 to the protein B7-H3 (CD276) in human pancreatic ductal adenocarcinoma (PDAC)." (PMID 34207408, 2021). "Notably, 100% of animals challenged with ER−, PR− HER2− SUM159 and MDA-MB-231 tumors exhibited complete and sustained tumor regression 6 months post treatment, suggesting that CD276 could be a critical target for triple-negative breast cancer (TNBC)." (PMID 38019654, 2023). "Here, we describe the development of a modified talirine PBD-based fully human CD276 ADC, called m276-SL-PBD, that is cross-species (human/mouse) reactive and can eradicate large 500–1,000-mm3 triple-negative breast cancer xenografts at doses 10- to 40-fold lower than the maximum tolerated dose." (PMID 38019654, 2023).
diffuse intrinsic pontine glioma (17 papers, 2021 to 2026). A neuroglial tumor that arises from the middle portion of the brain stem. "B7-H3 (CD276) is expressed on CNS tumors, and B7-H3-specific CAR-T cells were designed for therapy in diffuse intrinsic pontine glioma (DIPG), producing exciting results." (PMID 36937406, 2023).
Ewing sarcoma (16 papers, 2020 to 2025). A small round cell tumor that lacks morphologic, immunohistochemical, and electron microscopic evidence of neuroectodermal differentiation. "In a second model, CD276-WT athymic nude mice were subcutaneously challenged with ES4 Ewing’s sarcoma by implanting CD276-WT and -KO tumor cells on opposite flanks." (PMID 38019654, 2023).
liver cancer (16 papers, 2016 to 2025). An epithelial or non-epithelial malignant neoplasm that arises from the liver. "The positive regulation of JAK2/STAT3 signaling pathways has also implicated in CD276-mediated epithelial-to-mesenchymal transition in liver cancer." (PMID 27329595, 2016). "suggest that CD276 determines the malignancy and invasive ability of liver cancers through the JAK3/STAT3/SLUG signaling pathway involving MMP2." (PMID 33842369, 2021). "The expression of E-cadherin in CD276-knockout liver cancer cells is increased significantly suggesting that CD276 plays a key role in EMT, which is enables the metastasis of liver cancer cells." (PMID 33842369, 2021).
breast tumors (14 papers, 2014 to 2025). "The B7-H3 (CD276) immune checkpoint is a pancancer target that runs high on both the vasculature of breast tumors and cancer-associated fibroblasts." (PMID 41348261, 2025).
esophageal cancer (14 papers, 2016 to 2026). A primary or metastatic malignant neoplasm involving the esophagus. "To date, the exploration of CAR-T cells therapy in esophageal cancer has been limited, with only EphA2, HER2, MUC1, and CD276 being identified as potential therapeutic targets in preclinical studies." (PMID 40510363, 2025). "In 2019, a phase I clinical trial (NCT04025216) was underway to evaluate the safety and efficacy of CD276-targeting CAR-T cells in patients with advanced solid tumors, including esophageal cancer." (PMID 39417449, 2024). "The expression of CD276 was negatively correlated with the number of tumor-infiltrating CD8 + T cells, and the upregulated expression was related to the poor prognosis in esophageal cancer." (PMID 37592311, 2023). "Currently, the potential targets against esophageal cancer include MUC1, HER2, EpCAM, EpA2 and CD276, for CAR-T cell therapy, NY-ESO-1, MAGE-A3 and MAGE-A4 for TCR-T cell therapy." (PMID 34858843, 2021). "Cluster of differentiation 276 (CD276), which is a transmembrane protein that is involved in immune regulation and tumor progression is highly expressed in esophageal cancer tissues and cell lines, but not in normal tissues." (PMID 39417449, 2024).
meningioma (14 papers, 2018 to 2026). A generally slow growing tumor attached to the dura mater. "STAT1 and CD276 were highly expressed in malignant meningiomas compared with meningothelial meningiomas." (PMID 36203966, 2022).
squamous cell carcinoma (14 papers, 2019 to 2025). A carcinoma arising from squamous epithelial cells. "In squamous cell carcinoma, CD276 promoted evasion of immune surveillance by carcinoma stem cells and inhibited their clearance by CD8+ T cells." (PMID 38655053, 2024). "While, CD276 expression enables squamous cell carcinoma stem cells to evade immune surveillance and as an immunotherapy target for HNSC." (PMID 38617010, 2024). "In most malignant tumors, the KIFscore was found to be positively correlated with ULBP1, MICB, and CD276, among which, CD276 expression was reported to enable squamous cell carcinoma stem cells to evade immune surveillance." (PMID 37711200, 2023). "CD276 is involved in the immune escape of squamous cell carcinoma stem cells." (PMID 37037831, 2023). "In squamous cell carcinoma, tumour-initiating cells acquired the immune checkpoint molecules CD80 and CD276 to evade immunological surveillance from cytotoxic lymphocytes during local recurrence and metastasis." (PMID 37875589, 2023).
esophageal squamous cell carcinoma (13 papers, 2021 to 2026). Esophageal squamous cell carcinoma (ESCC) is a type of esophageal carcinoma (EC) that can affect any part of the esophagus, but is usually located in the upper or middle third. "Moreover, there is evidence for a correlation between CD276 expression and the intensity of Tregs infiltration in patients with esophageal squamous cell carcinoma." (PMID 37685876, 2023). "CD276 exhibited positive staining in 51.43% (54/105) and 51.35% (38/74) of stage III and IV esophageal squamous cell carcinoma (ESCC) patients, respectively, across all disease stages." (PMID 40705122, 2025). "In our immunohistochemistry staining of CD276 on normal control samples (adjacent esophageal epithelium located more than 2cm away from the proximal end of esophageal squamous cell carcinoma), we observed no detectable positive CD276 staining in the normal esophageal epithelium." (PMID 38566988, 2024).
small cell lung carcinoma (13 papers, 2021 to 2026). Small cell lung cancer (SCLC) is a highly aggressive malignant neoplasm, accounting for 10-15% of lung cancer cases, characterized byrapid growth, and early metastasis. "Early clinical trials of agents that block CD276 gave been initiated in small cell lung carcinoma and in other solid tumours." (PMID 40473819, 2025). "Recent advances in the molecular characterization of small-cell lung cancer (SCLC) have led to the identification of distinct transcriptional subtypes, defined by the differential expression of surface antigens such as SEZ6, DLL3, B7-H3 (CD276), TROP2 (TACSTD2), and CEACAM5." (PMID 41149456, 2025).
lymphoma (12 papers, 2020 to 2025). A malignant (clonal) proliferation of B- lymphocytes or T- lymphocytes which involves the lymph nodes, bone marrow and/or extranodal sites. "B7–H3 (CD276), one of the B7 superfamily molecules, is highly expressed in a variety of tumors, leading to poor patient prognoses, and it can participate in lymphoma immune escape by regulating cytotoxic lymphocyte activation." (PMID 35115487, 2022). "In addition, we found that the protein expression level of CD276 was highest in HNSC and PRAD, and lowest in carcinoid tumors, renal cancer and lymphoma." (PMID 36717836, 2023).
pancreatic adenocarcinoma (11 papers, 2021 to 2026). "The results of our research indicated that COL10A1 promotes tumorigenesis by modulating CD276 in pancreatic adenocarcinoma." (PMID 37974070, 2023). "Our research suggests that COL10A1 promotes pancreatic adenocarcinoma tumorigenesis by regulating CD276." (PMID 37974070, 2023). "B7-H3, also known as the CD276 antigen, was targeted by CAR T-cells in pancreatic adenocarcinoma in vitro and a metastatic xenograft mouse model, which proved efficacy." (PMID 35814023, 2022).